NUTM1 (NUT midline carcinoma family member 1)
Diseases named in the same sentence as NUTM1 in open-access papers (continued):
Sharing a sentence is not in itself a finding about the gene and the disease.
carcinoma (95 papers, 2006 to 2026). A malignant tumor arising from epithelial cells. "With the increased awareness and better availability of diagnostic methods such as the NUTM1 IHC and next-generation sequencing, NC is now considered a preferentially young adult cancer that can occur in any age group and many tissue sites." (PMID 38724194, 2024). "Although the exact function of NUTM1 is not yet completely known, it is associated with poorly differentiated epithelial carcinomas that commonly occur in young adults and show an aggressive growth dynamic especially when these cells carry the BRD4-NUTM1 fusion gene." (PMID 38793657, 2024). "However, because of the limited number of cases, it is unclear whether the reported NUTM1 fusion genes are the cancer driver or background mutations irrelevant to oncogenesis in these cases." (PMID 38724194, 2024). "The consistent induction of poorly differentiated carcinoma demonstrated a strong reprogramming activity of BRD4::NUTM1." (PMID 38724194, 2024). "Through analyzing hundreds of NC GEMM, our data demonstrated that when expressed at the endogenous level from an endogenous chromosome translocation, Brd4::Nutm1 can efficiently induce aggressive cancers with high penetrance." (PMID 38724194, 2024). "NUT (nuclear protein in testis) carcinoma is a type of poorly differentiated or undifferentiated malignancy defined by the rearrangement of the nuclear protein in testis (NUT) gene (also known as NUTM1)." (PMID 36936659, 2023). "Critically, BET proteins such as BRD4, which is part of a large portion of NUTM1 fusion proteins (>70%), have been widely studied as a therapeutic cancer target." (PMID 33562801, 2021). "Gene fusions involving the NUTM1 gene (NUT) represent defining genetic markers of a highly aggressive carcinoma type with predilection for the midline structures of children and young adults, hence the original description as NUT midline carcinoma." (PMID 32436169, 2020). "Many mutated genes from transplanted tumors encode proteins important for cell adhesion and transcription, among them the COSMIC-CGC cancer drivers Npm1, Nutm1, and Elf4." (PMID 30262843, 2019). "This analysis identified new contexts for fusion transcripts leading to overexpression of cancer genes located at the fusion 3′ end, such as NUTM1, RSPO2/3, and ROS1." (PMID 31097696, 2019). "In two transplantation lines (descending from C25 and E31) we observed the occurrence of new mutations in genes described as cancer drivers in COSMIC-CGC database, which are Rhoh, Npm1, Elf4, Ikbkb, and Nutm1." (PMID 30262843, 2019). "NMC is an aggressive and currently incurable carcinoma with a characteristic NUTM1 gene rearrangement." (PMID 29348827, 2017). "We identified one of the cell lines, RPMI2650, using expression data from the Genomics in Drug Sensitivity in Cancer Project (by screening for positive expression of NUTM1) and verified that this line indeed carries an NMC breakpoint." (PMID 29348827, 2017). "The nuclear protein in testis gene (C15ORF55 or NUTM1) is mainly known by its involvement with midline organs carcinoma." (PMID 24558400, 2014). "Similarly, the mechanisms underlying the multiple NUTM1 gene rearrangements have opened the door to better understand tumor pathogenesis and the role of NUT and other proteins in the epigenetics of this rare neoplasm and multiple other cancers." (PMID 35372003, 2022). "NUTM1-positive carcinoma has been found increasingly, and is now described in all ages." (PMID 34176480, 2021). "Although initially identified in a group of lethal midline carcinomas in which NUT forms fusion proteins with bromodomain proteins, NUTM1-rearrangement has since been identified in tumors at non-midline locations, with non-bromodomain partners and with varied morphology." (PMID 34898574, 2021).
carcinoma (continued). "Nuclear protein in testis (NUT) carcinoma is a rare but highly aggressive carcinoma, driven by genetic rearrangement of the NUT midline carcinoma family member 1 (NUTM1) gene on chromosome 15q14." (PMID 38389647, 2024). "Given the great success in drugs targeting cancer-driven fusion proteins such as Gleevec (targeting BCR-ABL in chronic myeloid leukemia), directly targeting the NUTM1 fusion proteins themselves is another promising avenue for targeted therapy." (PMID 33562801, 2021). "Other gene fusions involving transcription factors include NUT (or NUTM1), POU5F1, MAML2, NFIB, PLAG1, TFE3, NOTCH, and PAX8 fusions, imparting spatially and/or stochastically dysregulated expression in multiple different cancer types." (PMID 26684754, 2015). "This broad tissue distribution is a unique property of NC compared with many other fusion gene-driven cancers and indicates that the BRD4::NUTM1 fusion gene may transform a broad range of cell types covering all three germ layers." (PMID 38724194, 2024).
tumor (64 papers, 2015 to 2026). "Because Krt14-Cre remains active in NC cells, any residual floxed alleles would be deleted during tumor progression, making it highly improbable that a Brd4::Nutm1-positive tumor retains intact Sox2." (PMID 41266112, 2026). "Sinonasal NC presents typical undifferentiated or poorly differentiated cells, abrupt keratinization features and heterogeneous genotypes, including BRD4::NUTM1 and BRD3::NUTM1 fusions, with low tumor mutation burden and stable microsatellites." (PMID 38239638, 2023). "Because the malignancy is rare, little is known so far about the risk profiles associated with the diverse tumor origins and heterogeneous NUTM1 fusion partners." (PMID 35957893, 2022). "Interestingly, all of these patients likely had MYC-deregulated tumours, with high expression driven by NUTM1 rearrangement, stabilised by FBXW7 mutation or due to elevated MYC copy number or epigenetic mechanisms." (PMID 33311588, 2021). "A tdTomato-Luc2 reporter knocked in downstream of the testis-specific Nutm1 gene allows in vivo monitoring of tumor initiation and growth by bioluminescence imaging." (PMID 41266112, 2026). "The tumor diffusely expressed NUTM1, was positive for WT1cter at weak to moderate intensity, and was focally positive for CD99, while it was negative for keratins, EMA, P40, MyoD1, myogenin, NKX2.2, BCOR, and pan-TRK." (PMID 38851744, 2024). "At the gene expression level, fusion calling from RNA-sequencing data of six tumor samples again demonstrated Brd4::Nutm1 fusion with the designed junction as the only recurrent fusion." (PMID 38724194, 2024). "In an extraordinary case from a recent series, the patient survived for an impressive duration of 14 years post-positive identification of the NUTM1 break-apart in the tumor." (PMID 39200173, 2024). "Owing to the hallmark NUTM1 rearrangement of NC, diagnosis is usually made by immunohistochemical staining that recognizes the NUTM1 protein in the tumor tissue." (PMID 37049806, 2023). "In conclusion, sinonasal NC presents typical undifferentiated or poorly differentiated cells, abrupt keratinization features and heterogeneous genotypes, including BRD4::NUTM1 and BRD3::NUTM1 fusions, with low tumor mutation burden and stable microsatellites." (PMID 38239638, 2023). "While no clinical characteristics are specific for NC, some histologic features can be indicative; therefore, patients with these tumor characteristics should be routinely tested for NUTM1." (PMID 35957893, 2022). "While the normal function of the NUTM1 protein is related to spermatogenesis, overexpression of NUTM1 fusion genes leads to nuclear entrapment of the NUTM1 protein where it blocks cell differentiation and induces tumor growth." (PMID 35372003, 2022). "Nuclear grooves, as found in our case, have been described in one cytology report of a lung BRD3::NUTM1 fusion tumor, but nuclear pseudo-inclusions observed in our case on the cytology specimen have not been reported in NUT carcinomas." (PMID 34997561, 2022). "Immunohistochemistry for NUTM1 is clearly indicated in the assessment of a poorly differentiated pediatric tumor to confirm diagnosis, as well as the analysis of other genetic features to allow better counselling and consideration of novel treatment options." (PMID 34176480, 2021). "Furthermore, fusion calling from whole-genome sequencing of two paired datasets from tumor and normal liver DNA from the same tumor-bearing mice detected Brd4::Nutm1 as the only recurrent fusion gene in tumor tissues." (PMID 38724194, 2024). "This tumor is characterized by a chromosomal rearrangement involving NUTM1 gene." (PMID 36937407, 2023). "This patient’s tumor may represent another means (e.g., NUTM1 fusion) by which MYC overexpression compels oncogenesis in the neoplastic thyrocyte." (PMID 34997561, 2022). "These cases add to the expanding spectrum of NUTM1-rerranged neoplasia of the head and neck." (PMID 32436169, 2020).
tumor (continued). "The considerable heterogeneity in patient age, tumor location and type of NUTM1-fusion expressed suggests that NMC may ultimately be divisible into clinically relevant sub-groups, with different clinical outcomes and treatment responses." (PMID 29348827, 2017). "No BRD4::NUTM1 was expressed in NC surrounding normal epithelial or tumor-associated stromal cells." (PMID 38724194, 2024). "In this study, we have identified a few commonly mutated genes in pre-NACT tumor samples from either sensitive (DNAH5, CYP2D6, NUTM1) or resistant (CSPG4, TUBA3D, SLC35G5) cases, which suggest that these genes could have a potential utility for prediction of the response to NACT." (PMID 35501919, 2022). "The majority of these cases manifested a tumor with chromosomal translocation, which forms the BRD4-NUT fusion oncogene (n = 16), BRD3-NUT (n = 4), NSD3-NUT (n = 3), NUT-variant (n = 1), CHRM5-NUTM1 (n = 1) and other NUTM1 rearrangements (n = 5)." (PMID 36290813, 2022). "Immunofluorescence analysis in NC tumor tissue, primary NC cells, and cell lines ectopically expressing the BRD4-NUTM1 fusion gene demonstrated unequivocally that the NUTM1 fusion proteins form large foci in the cell’s nuclear region." (PMID 33562801, 2021). "Moreover, an NUTM1 fusion has not been previously reported in a tumor diagnostically consistent with MPNST." (PMID 39200173, 2024). "Unlike other NC markers, such as BRD4::NUTM1 and p63, which are diffusely expressed across most tumor cells, SOX2 is restricted to discrete subpopulations, often located near the tumor margin adjacent to the morphologically normal tissue." (PMID 41266112, 2026). "In Case 1, the NUTM1 break-apart signal was observed in 84% of tumor cells, whereas the tumor was negative for BRD4::NUTM1, SS18, and EWSR1 rearrangements." (PMID 38239638, 2023).
hematologic malignancies (2 papers, 2016 to 2025). "The NUT midline carcinoma family member 1 (NUTM1) gene is a fusion partner of growing interest in hematological disorders." (PMID 41373823, 2025). "Our findings add to the growing complexity of NUTM1 rearrangement’s role in hematologic malignancies and raise the possibility that the nature of the NUTM1 fusion partner or disease biology may influence the treatment response and clinical outcomes." (PMID 41373823, 2025).
prostate (1 paper, 2025). "High-throughput sequencing methods such as single-cell RNA-seq have enabled deep characterization of the prostate BCC genome, revealing key driver mutations of CASC5, NUTM1, PTPRC, KMT2C, and TBX3, genes also involved in chromatin remodeling and stem cell regulation." (PMID 40124187, 2025).
NUTM1 also shares sentences with these, for which no sentence is quoted: porocarcinomas (11 papers); undifferentiated carcinoma (6); adenocarcinoma (4); skin tumors (4); hidradenoma (3); mucoepidermoid carcinoma (3); primitive neuroectodermal tumor (3); breast carcinoma (2); head and neck carcinoma (2); hidradenocarcinoma (2); Lynch syndrome (2); neuroblastoma (2); spindle cell sarcoma (2); adenoid cystic carcinoma (1); adenosquamous lung carcinoma (1); adnexal carcinoma (1); B-cell precursor acute lymphoblastic leukemia (1); brain tumors (1); carcinoid tumours (1); carcinoid tumours of the lung (1); carcinoids (1); chronic lymphocytic leukemia (1); clear cell carcinoma (1); colon cancer (1); cylindroma (1); desmoplastic small round cell tumor (1); dysgerminoma (1); eccrine poroma (1); epithelial neoplasm (1); Ewing sarcoma (1).
A further 38 diseases each share a sentence with NUTM1 in 1 paper.